INS-IGF2 (INS-IGF2 readthrough)
Synonyms: INSIGF
Tractability: Antibody: its Gene Ontology location is reachable by antibodies, with medium confidence.
Gene: Protein-coding gene on chromosome 11 (2,132,538 to 2,161,209, reverse strand). Ensembl gene ENSG00000129965.
Subcellular location (Human Protein Atlas): Nucleoplasm; Predicted to be secreted
Gene Ontology:
Molecular function: hormone activity; insulin receptor binding
Biological process: signal transduction
Cellular component: extracellular region
Genetic constraint (gnomAD): Loss-of-function variants: 16 observed, 16.84 expected, observed/expected ratio (o/e) 0.95, 90% interval 0.64 to 1.44. The upper end of that interval is the gene's LOEUF score, 1.44, which puts it in group 5 of 6, group 1 being the genes least tolerant of losing a copy. Missense variants: 178 observed, 190.26 expected, observed/expected ratio (o/e) 0.94, 90% interval 0.83 to 1.06. Synonymous variants: 93 observed, 85.93 expected, observed/expected ratio (o/e) 1.08, 90% interval 0.91 to 1.29.
Diseases named in the same sentence as INS-IGF2 in open-access papers:
INS-IGF2 is named in the same sentence as 1 disease in open-access papers, as found by Europe PMC text mining. Sharing a sentence is not in itself a finding about the gene and the disease.
INS-IGF2 shares sentences with these, for which no sentence is quoted: malnutrition (1 paper).